ERBB3 (erb-b2 receptor tyrosine kinase 3)
Diseases named in the same sentence as ERBB3 in open-access papers (continued):
Sharing a sentence is not in itself a finding about the gene and the disease.
breast cancer (continued). "ZNF217 and ErbB3 expression levels showed significant correlation in human breast tumors, and ectopic ZNF217 expression induced ErbB3 protein overexpression in normal human mammary epithelial cells (HMECs) and in breast cancer cell lines (paired with increased ErbB2 expression)." (PMID 26431164, 2015). "ZNF217 also sensitized breast cancer cells to heregulin, the growth factor ligand for ErbB3." (PMID 26431164, 2015). "Furthermore, miR-125b was found to suppress the oncoproteins MUC1, ERBB2, and ERBB3, inhibiting the growth of breast cancer cells." (PMID 26693202, 2015). "ErbB3-dependent signal transmission relies on the dimerization partner ErbB2, a receptor tyrosine kinase that is frequently overexpressed and/or amplified in breast cancer cells." (PMID 25630670, 2015). "We have recently tested the hypothesis that MM-121 abrogates erbB3 signaling-mediated resistance to trastuzumab and paclitaxel in erbB2+ breast cancer cells via inactivation of erbB3 and its downstream PI-3 K/Akt signaling." (PMID 24886126, 2014). "Similar to the finding of TBK1 as a potent target for HER2-positive breast cancer, an identification of molecular targets regulated by ERBB3 signal pathways will be beneficial to design a new regime for ERBB3-targeted therapy or a combination therapy for treating colorectal cancers." (PMID 24970817, 2014). "Furthermore, we showed that miR-143/145 inhibited ERBB3 expression and consequently suppressed the proliferation and invasion of breast cancer cells." (PMID 25248370, 2014). "In breast cancer, both mRNA expression and protein levels of erbB3 are upregulated." (PMID 24886126, 2014). "Interestingly, miR-143 and miR-145 showed a cooperative repression of ERBB3 expression and cell proliferation and invasion in breast cancer cells, such that the effects of the two miRNAs were greater than with either miR-143 or miR-145 alone." (PMID 25248370, 2014). "Similarly, elevated expression of activated forms of Neu/ErbB-2 and ErbB3 are involved in the induction of mammary tumors in MMTV-Neu transgenic mice." (PMID 25516216, 2014). "We have published a series of articles indicating that estrogenic promotion of erbB2 kinase activity in mammary tumor cells requires erbB3, and the activation of erbB3 signaling plays an essential role in erbB2-mediated therapeutic resistance to tamoxifen, trastuzumab, and paclitaxel." (PMID 24886126, 2014). "We hypothesized that the high levels of ERBB3 are a consequence of miRNA regulation, and we subsequently identified a cluster of miRNAs, including miR-143 and miR-145, that directly target and regulate the expression of ERBB3 protein in breast cancer cells." (PMID 25248370, 2014). "Moreover, ErbB3 is more abundantly expressed than EGFR in normal breast tissue as well as in a vast majority of breast cancer cell lines including MCF7 and BT474 cells, making it a more likely dimerization partner for ErbB3 than EGFR." (PMID 24709902, 2014). "Finally, we showed that miR-143/145 inhibited ERBB3 expression and consequently promoted the proliferation and invasion of breast cancer cells, both in vitro and in vivo." (PMID 25248370, 2014). "In identifying the key downstream mediators through which erbB3 contributes to chemoresistance, we found that elevated expression of erbB3 conferred paclitaxel resistance in erbB2+ breast cancer cells via PI-3 K/Akt-dependent upregulation of Survivin, a critical inhibitor of apoptosis." (PMID 24886126, 2014). "We first determined the expression patterns of ERBB3 in human breast cancer tissues." (PMID 25248370, 2014). "Our data showed that inactivation of erbB3 signaling with MM-121 specifically downregulated Survivin in our in vitro models, and significantly enhanced paclitaxel-induced cytotoxicity and apoptosis in the otherwise resistant breast cancer cells." (PMID 24168763, 2013).
breast cancer (continued). "As MP-RM-1 inhibits both ligand-dependent and -independent activation of erbB3, we speculate that hMP-RM-1 might exert more potent antitumor activity than MM-121 against erbB2-overexpressing breast cancer." (PMID 24168763, 2013). "The activated form of ERBB3 was detected in human breast cancers with amplified ERBB2 expression." (PMID 23593223, 2013). "Taken together, our data indicate that the erbB3 blocking Ab MM-121 significantly enhances trastuzumab-induced growth inhibition in two erbB2+ breast cancer cell lines and exhibits potential to overcome trastuzumab resistance mainly through inactivation of the erbB3/PI-3K/Akt signaling." (PMID 24215614, 2013). "It is unclear whether an erbB3-targeted therapy may abrogate erbB2-mediated paclitaxel resistance in breast cancer." (PMID 24168763, 2013). "However, erbB3 has been shown to serve as a critical co-receptor of erbB2, and its expression is a rate-limiting factor for erbB2-mediated breast cancer cell survival and proliferation." (PMID 24168763, 2013). "We hypothesized that the anti-erbB3 Ab MM-121 can overcome trastuzumab resistance and enhance the efficacy of trastuzumab against erbB2+ breast cancer." (PMID 24215614, 2013). "In addition, activation of the erbB2/erbB3/PI-3K/Akt signaling also results in resistance to hormonal therapy and chemotherapy in breast cancer treatment." (PMID 24215614, 2013). "In addition to inducing paclitaxel resistance, the erbB2/erbB3/PI-3 K/Akt signaling also results in resistance to hormonal therapy and other chemotherapy in breast cancer treatment." (PMID 24168763, 2013). "Similar to human breast cancer, ERBB3 plays a central role in murine breast cancer models." (PMID 23593223, 2013). "We and others have also observed an elevated expression of the endogenous mouse erbB3 in the mammary tumors derived from erbB2/neu-transgenic mice; and the increased erbB3 forms physical and functional interactions with the transgene-encoded erbB2 to promote mammary tumorigenesis." (PMID 24168763, 2013). "Indeed ErbB3 mRNA levels relative to normal gland and measured by real-time PCR are increased in 46% of breast cancers and correlate positively with those for ErbB4 and negatively with EGFR mRNA." (PMID 22889873, 2012). "IGF1R and AR inhibitors are currently tested separately in the clinic in this context, whereas ERBB3 has not previously been linked to the biology of ER+ breast cancer." (PMID 22343619, 2012). "ErbB3 protein is detectable in 50–70% of human breast cancers by immunohistochemistry." (PMID 22889873, 2012). "Elevated expression of ERBB3 is frequently observed in breast cancer, which may play an important role in breast cancer progression and chemotherapy resistance." (PMID 23554686, 2011). "ErbB3 has been identified as a key partner for ErbB2, with this receptor heterodimer being identified as an oncogenic unit in breast cancer cells, whilst overexpression of ErbB4 has also been shown to promote growth of human breast cancer cells." (PMID 21396094, 2011). "Reduced expression of miR-148a in breast cancer cells leads to the elevation of ERBB3 expression to activate AKT and ERK1/2 signaling pathways, which may in turn increase p70S6K1 activation and HIF-1α expression." (PMID 23554686, 2011). "In the present study, using a panel of ER+ breast cancer cell lines, we examined for the first time whether IRS-1 can contribute to erbB3 signalling in breast cancer and what impact this may have on IGF-IR signalling." (PMID 21939528, 2011). "In contrast, ErbB3 localised at the membrane can heterodimerize with other ErbB family members, principally ErbB2, in response to ligand stimulation to potently promote breast cancer cell growth." (PMID 21396094, 2011). "In addition, suppression of v-erb-b2 erythroblastic leukemia viral oncogene homolog 2 (ERBB2) and ERBB3 by enforced expression of miR-125a or miR-125b resulted in impaired anchorage-dependent growth in breast cancer cells." (PMID 21394831, 2011).
breast cancer (continued). "A potential consequence of the ability of HRGβ1/erbB3 signalling to suppress IGF-IR signalling activity is that such a mechanism could severely affect the efficacy of IGF-IR-targeted agents in these breast cancer cells." (PMID 21939528, 2011). "In the present study, we have investigated whether induction of ErbB3 and/or ErbB4 may provide an alternative resistance mechanism to antihormonal action in a panel of four oestrogen receptor (ER)-positive breast cancer cell lines." (PMID 21396094, 2011). "One possible mechanism was recently identified by Gijsen and colleagues, who reported that blockade of Akt can activate ADAM17 (ADAM metallopeptidase domain 17) in erbB2-overexpressing breast cancer cells, leading to release of heregulins, which can act in an autocrine manner to activate erbB3." (PMID 21939528, 2011). "Consequently, cotargeting IGF-IR and either erbB3 or IRS-1 should prove to be a more effective strategy for the treatment of ER+ breast cancer." (PMID 21939528, 2011). "In this study, we examined whether IRS-1 also associates with another erbB receptor family member, erbB3, and what impact this might have on IGF-IR signalling in three ER+ breast cancer cell lines." (PMID 21939528, 2011). "For instance, the levels of MiR-206 have been found to be higher in ERalpha-negative MB-MDA-231 cells than in ERalpha-positive MCF-7 cells, and enforced expression of miR-125a or miR-125b leads to coordinate suppression of ERBB2 and ERBB3 in the human breast cancer cell line SKBR3." (PMID 21192833, 2010). "On the basis of multiple lines of evidence, we hypothesised that the ErbB2/ErbB3 heterodimer would be a valuable target for the development of a bsAb for the treatment of breast cancer." (PMID 18841159, 2008). "In patients, high levels of ErbB3 expression predict early escape from trastuzumab therapy, and escape of at least six different breast cancer cell lines from small-molecule TKIs in vitro correlates with activation of ErbB3 and concomitant signalling through the Akt pathway." (PMID 18841159, 2008). "The ErbB2 and ErbB3 receptors are frequently co-expressed in human breast cancer, but potentially more indicative of the importance of ErbB2/ErbB3 heterodimers in driving breast cancer progression is the link between escape from ErbB2-targeted therapies and a gain in ErbB3 activity or expression." (PMID 18841159, 2008). "Since α6β4 regulates ErbB-3 level and the depletion of either β4 or ErbB-3 proteins resulted in a strong inhibition of Akt activation, the data confirm the essential role of ErbB-3 in the activation of Akt by α6β4 integrin in mammary tumor cells." (PMID 18270579, 2008). "This gives rise to the hypothesis that expression of activated Akt could compensate for the expression of ErbB3 in ErbB2-induced mammary tumours." (PMID 18700973, 2008). "Taken together, our results suggest that bispecific targeting of ErbB2 and ErbB3 with ALM may be efficacious in vivo against breast cancers with a wider range of ErbB2 expression than those amenable to the trastuzumab therapy available at present." (PMID 18841159, 2008). "The importance of ErbB3 expression in breast cancer has been recently highlighted by the demonstration that continued oncogenic signalling through ErbB3 in human breast cancer cell lines results in the failure of gefitinib to completely inhibit the kinase activity of ErbB2." (PMID 18283314, 2008). "We have demonstrated that HRGβ1 can partially overcome the inhibitory effects of gefitinib monotherapy on growth and invasion of tamoxifen-resistant MCF-7 breast cancer cells through promotion of erbB3/erbB2 heterodimerization and activation of the PI3K/AKT signalling pathway." (PMID 17686159, 2007). "Furthermore, this combination treatment was shown to increase erbB3 activity in erbB2-overexpressing breast cancer cells." (PMID 17686159, 2007).
breast cancer (continued). "Indeed, it has been reported that basal levels of erbB2/erbB3 heterodimers are greatly reduced following treatment of BT-474 breast cancer cells with gefitinib, resulting in a substantial blunting of response to HRGβ1 treatment." (PMID 17686159, 2007). "While others have reported that transgenic mice bearing activated forms of rat c-neu/erbB2 have co-expression of erbB2 and endogenous erbB3 in mammary tumors, direct physical and functional interactions between these two species receptors have not previously been reported." (PMID 16168116, 2005). "Although Ebp1 was shown to be associated with ErbB3 in breast cancer cells, the interaction of Ebp1 with ErbB3 in prostate cells had not yet been demonstrated." (PMID 15583694, 2005). "Since both erbB2 and erbB3 were highly expressed by our mammary tumor cell lines and HRG-promoted tumor cell proliferation, we sought physical evidence that the wt-rat-neu/ErbB2 could form a complex with the endogenous mouse erbB3." (PMID 16168116, 2005). "We next determined if ErbB3 could bind Ebp1 in human prostate cell lines as it does in breast carcinoma cells and if HRG could affect this binding." (PMID 15583694, 2005). "In addition, the AP-2α deletion mutant, which can saliently interfere with the transcriptional activation function of each AP-2 member, not only inhibited the ErbB3 promoter activity but also suppressed ErbB3 transcription in the ErbB3-overexpression breast cancer cell lines." (PMID 38835349, 2024). "On the other hand, most ERBB3 mutations occurred in breast cancers without HER2 over-expression." (PMID 37760445, 2023). "Alterations in the ErbB family (namely ErbB1 (EGFR/HER1), the orphan receptor ErbB2 (HER2 or Neu), ErbB3 (HER3), and ErbB4 (HER4)) have been associated with BC incidence and poor prognosis and mutations of ErbB effectors are among the most common genetic abnormalities associated with breast cancer." (PMID 36233192, 2022). "Thus, we examined this idea with miR-125a and miR-205 in order to determine whether co-expression of the two miRNAs would exert functional cooperation to inhibit erbB3 expression in HER2-over-expressing breast cancer cells." (PMID 30930695, 2019). "Collectively, these data suggested that the expression of miR-125a, miR-125b, and/or miR-205 could be specifically increased in breast cancer cells; and two miRNAs, especially miR-125a and miR-205 showed functional cooperation to suppress erbB3 expression in HER2-overexpressing breast cancer cells." (PMID 30093840, 2018). "Thus, we first investigated whether inhibition of erbB3 expression with the miRNA cluster could enhance the anti-proliferative effects of trastuzumab on HER2-overexpressing breast cancer cells." (PMID 30093840, 2018). "Mutations in EGFR, ERBB2, Erb-B2 receptor tyrosine kinase 3 (ERBB3) and Erb-B2 receptor tyrosine kinase 4 (ERBB4) (referred to hereinafter as ERBB family mutations) either occur alone or co-occur with PIK3CA mutations in 19% of HER2-positive breast cancers (n = 58)." (PMID 28750640, 2017). "This suggests that PPM1H and ERBB3 may have some link with HER2 type breast cancer." (PMID 29322925, 2017). "Thus, when we evaluate the impact of erbB3 on clinical outcome of breast cancer patients, it would be better to consider not only its expression and interactions with other RTKs like erbB2, but also its subcellular distribution as well as the expression levels of HRG." (PMID 24886126, 2014). "However, very little is known about the regulation of ERBB3 expression in breast cancer." (PMID 25248370, 2014). "Thus, ERBB3 is likely to become a focus of breast cancer treatment." (PMID 25248370, 2014). "We next investigated whether miR-143/145 were inversely correlated with ERBB3 in breast cancer." (PMID 25248370, 2014). "However, the prognostic value of erbB3 expression in breast cancer has been controversial." (PMID 24886126, 2014). "Thus, ERBB3 offers a particularly promising molecular target for breast cancer therapy." (PMID 25248370, 2014).
breast cancer (continued). "Therefore, we investigated whether the HRG-β1 and ErbB3 activate Smad2 signaling during process of EMT in breast cancer cells." (PMID 23937725, 2013). "Because MM-121 mainly inhibits activation of erbB3 and Akt in erbB2-overexpressing breast cancer cells, it is conceivable to hypothesize that MM-121 may abrogate erbB3 signaling-mediated therapeutic resistance to tamoxifen, trastuzumab, and other chemotherapeutic agents, such as doxorubicin." (PMID 24168763, 2013). "To explore whether the anti-erbB3 Ab MM-121 may enhance the activity of trastuzumab against erbB2+ breast cancers, we investigated the combinatorial effects of MM-121 and trastuzumab on erbB3 signaling and cell proliferation in two erbB2+ breast cancer cell lines (SKBR3 and BT474)." (PMID 24215614, 2013). "Therefore, we suggest that blockade of the EMT mechanisms by HRG, including ErbB3 and not only Snail but also Smad2, might be a useful therapeutic target in breast cancer." (PMID 23937725, 2013). "Heregulin, a ligand of HER receptors and more specifically of ErbB3 and ErbB4, which is essential for ErbB2 phosphorylation in response to heregulin, is involved in the progression of different types of human cancers and induces the spread of breast cancer cells in vivo." (PMID 22952755, 2012). "Furthermore, by using human breast cancer cell lines and a series of breast cancer biopsies from patients undergoing tamoxifen therapy, it was found that α6β4 integrin contributes to tamoxifen resistance via induction of ErbB-3 expression, which leads to an increase in AKT activation." (PMID 22567280, 2012). "miR-148a attenuates angiogenesis likely through directly inhibiting ERBB3 for transmitting the signals to its downstream signaling molecules.Our findings suggest that miR-148a/ERBB3 pathway would be a promising therapeutic target for breast cancer in the future." (PMID 23554686, 2011). "In the present study, we examined whether IRS-1 can associate with other erbB family members, notably erbB3, and whether this has a direct impact on IGF-IR signalling in three ER+ breast cancer cell lines (MCF-7, T47D and BT-474) previously shown to express IRS-1 protein." (PMID 21939528, 2011). "Furthermore, blockade of ErbB3 expression using an artificial transcription factor, E3, inhibits breast cancer cell growth and targeted downregulation of ErbB4, using either ribozymes or small interfering RNA, can reduce the growth of MCF-7 and T47D cell lines both in vitro and in vivo." (PMID 21396094, 2011). "Thus, ERBB3 could be not only a predictor of good prognosis within ER-positive sporadic and familial breast cancer patients but also a putative therapeutic target for these tumours." (PMID 19826428, 2009). "In breast cancer, the pan-ERBB inhibitor Neratinib (excluding ErbB3) enhances ferroptotic cell death." (PMID 40846695, 2025). "Heterotrimerization of erbB3/erbB2/IGF-IR blocked trastuzumab binding and activated PI3K/AKT signaling pathway and Src kinase, which resulted in trastuzumab resistance in breast cancer cells." (PMID 38835349, 2024). "Interaction of L1CAM and the erbB3 receptor was reported to enhance the response of erbB3 to the EGF-like factors, neuregulins, in MCF-7 breast cancer cells." (PMID 38263290, 2024). "Of note, NRG1 is a well-known activator of ERBB3/ERBB2 dimers, which are known to play a role in the context of HER2+ breast cancer aggressiveness." (PMID 35664762, 2022). "In this study, we elucidated that circEPSTI1 acts on ERBB3 by adsorbing miR-145, thereby promoting the proliferation, migration, and invasion of HER2-positive breast cancer cells." (PMID 36059813, 2022). "We demonstrate that the Ad-mediated expression of shErbB3 could induce persistent silencing of ErbB3 and downregulation of its oncogenic signaling axis in in vitro models of breast cancer and that was well translated in in vivo tumor growth assays using a breast cancer xenograft model." (PMID 35806132, 2022).